NRAS (NRAS proto-oncogene, GTPase)
Diseases named in the same sentence as NRAS in open-access papers (continued):
Sharing a sentence is not in itself a finding about the gene and the disease.
cutaneous melanoma (continued). "First, in cutaneous melanoma samples from TCGA and GEO, the differentiation of samples with or without resistance to targeted therapy and immune therapy was not considered, nor were BRAF/NRAS mutations in patient tumors." (PMID 36713580, 2022). "Most studies put forward that unlike human cutaneous melanomas, human and canine mucosal melanomas are more often associated with high copy number alterations, lower TMB, and structural variation burden rather than the high specific hotspot gene mutations (BRAF or NRAS) seen in cutaneous humans." (PMID 39408717, 2024). "A mutagenic effect of UV irradiation could be demonstrated after UV irradiation of a cloned human NRAS proto-oncogene in vitro and subsequent transfection, leading to the codon 61 Q61R (CAA/CGA) and Q61K (CAA/AAA) changes that are identical to those found in cutaneous melanoma samples." (PMID 31398831, 2019). "However, the relationship between UVR and cutaneous melanoma is not yet fully understood, given the absence of a UV DNA damage signature in genes relevant to cutaneous melanoma such as BRAF, NRAS, or CDKN2A (cyclin dependent kinase inhibitor 2A)." (PMID 35682684, 2022).
leukemia (107 papers, 2009 to 2026). A malignant (clonal) hematologic disorder, involving hematopoietic stem cells and characterized by the presence of primitive or atypical myeloid or lymphoid cells in the bone marrow and the blood. "In preclinical studies, it has been demonstrated that FLT ITD and NRAS mutations accelerate KMT2A leukemia onset, possibly by providing stimulatory factors." (PMID 41514668, 2026). "As a novel regulator for APA events, FIP1L1 can regulate the 3’UTR lengthening of leukemia-associated genes, including NRAS, BAALC, and MAPKAPK3." (PMID 34195183, 2021). "Approximately two-thirds of CBF leukemia cases harbor activating mutations in NRAS, KIT, FLT3, KRAS, PTPN11, and/or loss-of-function mutations in NF1." (PMID 34331016, 2021). "Unexpectedly, BM blasts obtained the new NRAS mutations after VA treatment, and consequently experienced leukostasis with two distinct leukemia clones." (PMID 33292606, 2020). "DNA analysis of 5 leukemia samples (TH01_0124_S01, TH01_0134_S01, TH03_0010_S01, TH03_0010_S02, and TH03_0011_S01) identified an activating mutation in NRAS (OMIM 164790)." (PMID 31651965, 2019). "Meanwhile, NRAS mutation was associated with adverse prognosis and increased risk of leukemia transformation in MDS." (PMID 29029494, 2017). "Further, the significant co-occurrence of KRAS and NRAS codon 12 and 13 microclonal mutations suggests the existence of a highly-heterogeneous subset of Ras-driven leukemias." (PMID 27683039, 2016). "Nonetheless, our data are consistent with the notion that RAB27B plays a critical role in leukemia cell growth when NRAS is required — such as in AMLs with oncogenic NRAS or CBL mutations — while it is dispensable for the growth of AMLs with other dominant mutations or in normal HSPCs." (PMID 37317963, 2023). "However, the pattern of NRAS mutations in leukemia varies widely from solid tumors with a predominance for the observed p.(Gln61) (38%) and p.(Gly12) (36%) missense mutations." (PMID 37384296, 2023). "The use of multiple NRAS-mutant leukemia cells may allow for more NRAS mutation-specific screening to elucidate the full extent of NRAS signaling." (PMID 36358254, 2022). "However, the majority of FLT3-TKD and NRAS mutations presented in the primary leukemia were loss at relapse." (PMID 33577442, 2021). "We could speculate the existence of a clone with the KMT2A/AFF1 fusion, which competes with the NRAS-mutated clone and initiates the leukemic process, and a minor, which may accelerate the development of the overt leukemia." (PMID 34575904, 2021). "Our focused studies on EZH2 and NRAS mutations provide an opportunity to dissect how distinct oncogenic pathways converge at the single-cell and single-gene levels to cause aberrant gene expression and leukemia progression." (PMID 34732703, 2021). "Hence, the observed immature T-ALL phenotype in our conditional bone marrow transplant models is the result of the fusion blocking T-cell differentiation and the NRAS(G12D) mutation providing the necessary proliferative signals for leukemia development." (PMID 34230493, 2021). "Interestingly, we found that one patient harbored both KRAS (G12C) and NRAS (G12D) mutations simultaneously with AFs less than 0.2, implying that at least two leukemia clones existed, however the patient with primary bone marrow blasts more than 97%." (PMID 32164600, 2020). "One of the private SNVs in this third leukemia was an NRAS gain-of-function mutation, which occurs commonly in human T-ALL7,8,19, and thus these findings would suggest that clonal evolution similar to that which occurs in natural disease is operative in this synthetic model." (PMID 31266935, 2019). "Indeed, type I mutations are common in NUP98 rearranged leukemia, including mutations in the NRAS, KRAS, KIT, WT1 and FLT3 genes." (PMID 23332017, 2013). "Notably, RAB27B was important for the growth of leukemia cells with CBL or NRAS mutations." (PMID 37317963, 2023).
leukemia (continued). "MM harbors both oncogenic activating mutations of KRAS and NRAS 1, and while ALL and AML also harbor KRAS A146 mutations, these leukemias preferentially express mutant forms of NRAS44." (PMID 41542462, 2026). "In mutation models, anti-PD-1 treatment has limited effect on relieving T cell suppression and the recovery of anti-leukemia immune responses is also limited, suggesting that NRAS mutant AML evades immune system surveillance through multiple mechanisms." (PMID 40861464, 2025). "Our study shows that GOLGA7 serves as a safe and effective therapeutic target for NRAS‐driven leukemia." (PMID 40091521, 2025). "In contrast, other genomic abnormalities, including mutations in FLT3, NRAS, and RUNX1, tend to be acquired later during leukemia development." (PMID 39590121, 2024). "It has been established that palmitoylation regulates the trafficking of NRAS between the Golgi and the PM, and palmitoylation of oncogenic NRAS is essential for leukemia progression." (PMID 37317963, 2023). "For instance, the specific palmitoylation sites of NRAS and the palmitoyl thioesterases of NRAS have yet to be identified in leukemia." (PMID 37317974, 2023). "The requirement for palmitoylation of RAS proteins in NRAS-driven leukemia has been demonstrated in the NRASG12D model, which reflects a common NRAS mutation in human myeloid malignancies." (PMID 37317974, 2023). "NRAS/KRAS mutations frequently emerge at relapse in patients treated with clinical FLT3 inhibitors, and Ras oncoprotein expression rescues FLT3-mutant leukemia cell lines from drug-induced apoptosis." (PMID 37681415, 2023). "NUP98 mutations in leukemias are associated with mutations affecting apoptosis, such as BCR-ABL, NRAS, or KRAS and ICSBP (also known as IRF8)." (PMID 35107131, 2022). "Probably, the most common alterations in leukaemia are those found in the RAS/MAPK pathway (50% of relapsed B-ALL, 15% of T-ALL and 50% of AML), such as KRAS, NRAS and PTPN11 mutations." (PMID 35743666, 2022). "The cells were generated by knocking out endogenous NRAS with CRISPR/Cas9 and introducing an exogenous Dox-regulated NRASG12V expression vector into leukemia cells carrying the NRASG12D mutation and whose growth depended on the NRAS signaling pathway." (PMID 36358254, 2022). "Compared with other subtypes of leukemia, acute leukemia with KMT2A translocations (such as KMT2A-AF4, and KMT2A-AF9) harbored the fewest number of mutations, in which NRAS mutations commonly co-occur." (PMID 36213638, 2022). "The unusual oncogenic role of PTEN in the pre-B ALL model was described in the context of Bcr/Abl- and NRas-mediated leukemia initiation, both strong oncogenes on their own." (PMID 35459737, 2022). "Recipient mice that received TCF7-SPI1 + NRAS(G12D) developed leukemia (median disease-free survival = 66 days) with a similar latency to those that received NRAS(G12D) alone (median disease-free survival = 74 days)." (PMID 34230493, 2021). "Here the authors analyze leukemia mouse models with both oncogenic NRAS and EZH2 mutations using single-cell RNA-sequencing, evaluate oncogenic cooperation, and identify GEM as a regulator of leukemia-initiating cells." (PMID 34732703, 2021). "Although NRAS(G12D) alone and TCF7-SPI1-P2A-NRAS(G12D) both gave rise to leukemia with a similar latency, a clear difference was observed in disease presentation and immunophenotype." (PMID 34230493, 2021). "The mutation frequency of known CBF leukemia associated genes was similar to previous reports; Most common were missense mutations of RAS-genes, present in 57% of the patients (43% NRAS, 19% KRAS), affecting the known hotspots (G12, G13, Q61)." (PMID 31896782, 2020). "Through kinome profiling, we found that TP-0903 inhibited both ACK1 and GCK kinases, which have been reported to synergistically contribute to the growth of NRAS mutant leukemia cells." (PMID 33268594, 2020).
leukemia (continued). "Taken together, it is likely that inhibition of ACK1 and GCK kinases contributes to the activity of TP-0903 in NRAS mutant leukemia cells." (PMID 33268594, 2020). "We focused our efforts on FLT3ITD, FLT3N676K, and NRASG12D, as FLT3 and NRAS are the most common targets of mutations that deregulate signal transduction in AML, and studied clonal evolution of leukemia cells carrying subclonal activating mutations over time." (PMID 29720585, 2018). "An inducible NRAS(V12)-driven AML mouse model has established a critical role for continued NRAS(V12) expression in leukemia maintenance." (PMID 27991934, 2017). "Two separate studies in 1994 first described Kirsten rat sarcoma viral oncogene homolog (KRAS) and neuroblastoma RAS viral (v-ras) oncogene homolog (NRAS) mutations in the blood of pancreatic carcinoma and leukemia patients." (PMID 27056366, 2016). "Palmitoylated oncogenic NRAS is a proposed target for developing therapies against NRAS-associated malignancies like acute myeloid leukemia (AML) as well as other types of NRAS-amplified leukemias." (PMID 22312457, 2011). "The mice transplanted with bone marrow cells expressing oncogenic human NRAS protein developed a leukemia-like disease and died within a few months, while the mice transplanted with cells expressing palmitoylation mutant of NRAS did not develop such a disease and stayed healthy." (PMID 40733034, 2025). "We also examined the impact of constitutive Golga7 knockout on normal development and physiology in mice to ascertain whether GOLGA7 serves as a safe and effective therapeutic target for NRAS‐driven leukemias." (PMID 40091521, 2025). "To determine whether TAUT is broadly required for de novo AML growth, we tested the impact of its loss on initiation of leukaemia driven by MLL-AF9/NRAS(G12V) and by AML-ETO9a/NRAS(G12V)." (PMID 40369079, 2025). "Several studies have suggested that specific genetic mutations, including those involving RAS pathway genes such as NRAS, could influence the extramedullary involvement of leukemia, potentially including the skin." (PMID 38363781, 2024). "A recent genome-wide CRISPR screening study identified GOLGA7 as a NRAS co-dependent gene in leukemia cell lines with or without NRAS mutation." (PMID 38317235, 2024). "Thus, our results revealed what we believe to be a previously unappreciated role for RAB27B in regulating NRAS activity, signaling, and leukemia cell growth." (PMID 37317963, 2023). "While certain mutations (e.g., DNMT3A, TET2, and ASXL1) are frequently observed in clonal hematopoiesis and seem to occur relatively early in leukemogenesis, others tend to emerge later during the progression of leukemia, they include mutations in FLT3, NRAS, and RUNX1." (PMID 37958832, 2023). "NRAS and also ASXL1, RUNX1, and SETBP1 gene mutations were proved to be independent risk factors for inferior OS and the increased risk of MDS progression to leukemia." (PMID 36982819, 2023). "RAB27B regulates NRAS activity, signaling, and leukemia cell growth." (PMID 37317963, 2023). "Importantly, restoration of Socs2 expression significantly mitigated growth of NRAS mutant leukemia cells." (PMID 35352806, 2022). "These molecules are expected to be new therapeutic targets for NRAS-mutant leukemia cells." (PMID 36358254, 2022). "These genes contribute to the proliferation of the leukemia cell THP-1 and may be new therapeutic targets for NRAS-mutant leukemia cells." (PMID 36358254, 2022). "NRAS gene was found to be a protective prognostic factor in one study on leukaemia." (PMID 35444210, 2022). "These molecules are promising new therapeutic targets for NRAS-mutant leukemia." (PMID 36358254, 2022). "The combination also resulted in a more immature immunophenotype than mutated NRAS alone with a double negative leukemia (CD4− and CD8−), similar to the immunophenotype of the patient X09." (PMID 34230493, 2021).
leukemia (continued). "This assumption is in line with previous studies showing that treatment with N-acetyl cysteine, which exerts antioxidant activity by augmenting cellular thiols, reduces DSBs and facilitates non-homologous end joining repair in bone marrow cells in a murine NRAS/BCL2-related model of leukemia." (PMID 30323311, 2019). "Others have shown that non-hotspot KRAS and NRAS mutations occurring in leukemias and rare ERBB2 mutations in lung cancer are functionally transforming." (PMID 23237847, 2013). "A contributing factor may be the high proliferative state of leukemia stem cells (LSCs) in pAML, with activated RAS signaling pathways, which could explain the elevated mutation frequencies in RAS pathway genes such as NRAS, KRAS, and PTPN11." (PMID 41294667, 2025). "Notably, RAB27B is important for the growth of leukemia cells with CBL or NRAS mutations but does not affect normal hematopoiesis." (PMID 37317963, 2023). "Common leukemia-associated genes have been identified by the investigation of gene sets obtained by comparison of analysis 1 with analysis 3 [FLT3 and C-terminal binding protein 2 (CTBP2)] and analysis 2 with analysis 3 [NRAS and GATA binding protein 2 (GATA2)]." (PMID 29221109, 2017). "By regulating NRAS palmitoylation, RAB27B facilitates ERK signaling activation to promote leukemia development." (PMID 39877903, 2025). "In leukemia cells, RAB27B, a RAB family small GTPase, promotes the palmitoylation of NRAS, and the effect of RAB27B on NRAS palmitoylation relies on ZDHHC9, which interacts with RAB27B." (PMID 39877903, 2025). "Specifically, in the NRAS^G12D mutant AML mouse model, hematopoietic stem/progenitor cells upregulated the expression of MHC class molecules, driving a potent anti-leukemia response." (PMID 40861464, 2025). "However, NRAS mutations in JMML are often associated with higher relapse rates, warranting adjusted post-transplant treatment strategies, including low-intensity graft versus host disease (GVHD) prophylaxis to enhance the graft versus leukemia (GVL) effect and reduce the risk of relapse." (PMID 38658558, 2024). "We showed in this study that RAB27B depletion dramatically reduced NRAS palmitoylation, activity, and downstream RAF/MEK/ERK signaling in both leukemia cell lines and primary human AMLs." (PMID 37317963, 2023). "Mutations in the receptor tyrosine kinase genes KIT and FLT3 and the proto-oncogenes NRAS and KRAS have been observed in up to 80% of CBF leukemia patients and probably serve as cooperating factors during leukemogenesis promoting proliferation." (PMID 31896782, 2020). "Expression of mutant NRAS and FLT3 in the mouse leukemia cell line Ba/F3 resulted in elevated phosphorylated p-AKT and p-ERK1/2, as well as p-STAT5 for FLT3ITD." (PMID 29720585, 2018). "Yet, we found that EZH2 was capable of generating leukemia in mice even in the absence of IDH1 or NRAS." (PMID 40362463, 2025). "NRAS G12V is required in the leukemia self-renewal process, independent of its effects on growth and survival." (PMID 36213638, 2022). "Palmitoylation is essential for oncogenic NRAS signaling, as mice transplanted with cells overexpressing a nonpalmitoylatable NRAS mutant remain healthy and do not develop leukemia." (PMID 34983949, 2022). "Instead, oncogenic N-Ras reduces the active enhancer marker H3K27ac at the SOCS2 locus, which may explain the lower gene expression of SOCS2 in NRAS mutant leukemia cells." (PMID 35352806, 2022).
leukemia (continued). "Because higher miR-181a levels are associated with improved outcomes in AML, and because miR-181a downregulation contributed to leukemia growth and directly targeted KRAS, NRAS and MAPK1, we reasoned that increasing miR-181a may have therapeutic value in AML." (PMID 27517749, 2016). "Although the co-occurrence of NRAS mutations and AML1/ETO expression remains elusive, all of these reports suggest that KIT mutants play important roles in CBF leukemia, with negative impacts on the clinical course." (PMID 21917154, 2011). "Interestingly, leukemia 241 showed concomitant JAK3 (p.R653H) and NRAS (p.G13S) activation." (PMID 40394211, 2025). "The resulting leukemias were further phenotyped using flow cytometry with NRAS(G12D) leukemic thymic cells having a more differentiated CD4+/CD8+ immunophenotype and TCF7-SPI1 + NRAS(G12D) leukemic cells a CD4−/CD8−, (intracellular) CD3+ and CD117+ immature immunophenotype." (PMID 34230493, 2021). "These include mutations in genes known to cooperate with CBF-rearrangements [e.g. NRAS (n = 6), KRAS (n = 4), FLT3 (n = 2), KIT (n = 3), ZBTB7A (n = 2)] as well as in genes, which have not been described to be mutated in CBF leukemia so far (e.g. ZFHX4, NFE2, HERC1)." (PMID 31896782, 2020). "Among RASmut MLL-AF4 rearranged leukaemia specimens at diagnosis, 69.5% were characterized by ≥2 different clones with a distinct RAS mutation in the mutation hot spot regions, which also means that KRAS and NRAS mutations are not mutually exclusive." (PMID 27698462, 2016). "Furthermore, enforced expression of another MLL fusion protein, MLL-AF9, and other non-MLL leukemia drivers, including AML1-ETO, MYC, and NRAS in primary HSPCs, show that the upregulation of Igf2bp3 is specific to MLL-Af4." (PMID 34321607, 2022). "However, unlike NRAS, palmitoylation-defective KRAS4A still induces leukemia in mice, albeit with a much longer latency." (PMID 26715448, 2015).